STAT3 (signal transducer and activator of transcription 3)
Diseases named in the same sentence as STAT3 in open-access papers (continued):
Sharing a sentence is not in itself a finding about the gene and the disease.
colorectal cancer (continued). "For example, STAT3 has been found to be involved in colorectal cancer cell growth, survival, invasion, and migration through regulation of gene expression, such as Bcl-2, p21waf1/cip1, p27kip1, E-cadherin, VEGF, and MMPs." (PMID 34638708, 2021). "In another report, there was a 4.5-fold high expression of miR-2276 in colorectal cancer cells that were silenced for STAT3." (PMID 34141710, 2021). "Exosomal transfer of p‐Stat3 induces 5‐FU resistance in colorectal cancer cells by mitigating activation of the caspase cascade of apoptosis." (PMID 34766149, 2021). "ATL-1 was found to inhibit melanoma and colorectal cancer cell proliferation via the JAK2/STAT3 or AKT/mTOR signaling pathway." (PMID 34692516, 2021). "In liver cancer, in addition, the up-regulation of hypoxia factors suppresses the expression of miR-199a-5p and promotes glycolysis, while in colorectal cancer, miR-155 promotes the Warburg effect via the IL-6/STAT3 pathway." (PMID 34298698, 2021). "Here, we propose a novel signaling pathway of Oct4 in cell survival, in addition to Stat3/survivin signaling in murine embryonic stem cells and chemoresistant colorectal cancer cells." (PMID 34685622, 2021). "This is the result of cinobufagin inhibiting the epithelial-mesenchymal transition in colorectal cancer by inhibiting the STAT3 pathway." (PMID 34769467, 2021). "On the one hand, Kitamura et al49 demonstrated that downregulation of HLA class II expression induced by interleukin-6/STAT3 signaling activation hampered dendritic cells activating effector T cells in colorectal cancer." (PMID 34362829, 2021). "The study aimed to evaluate the possible modulation of Nrf2, NF-ĸB and STAT3 signaling pathways in the colorectal cancer (CRC) cells line DLD-1 and HCT116 by secondary metabolites of lichens." (PMID 34443375, 2021). "The STAT3 pathway has been shown to participate in the promotion of colorectal cancer cell invasion induced by TRIM14." (PMID 33982666, 2021). "The nuclear PKM2, an isoform of muscle type of pyruvate kinase that is involved in a cancer-specific metabolism, activates nuclear STAT3 that correlates with gefitinib resistance in colorectal cancer cells." (PMID 33392396, 2021). "Prolonged or excessive inflammatory response through STAT3 overactivation contributes to chronic inflammation, resulting in an inflammatory disorder and colorectal cancer." (PMID 33633749, 2021). "In colorectal cancer, TAMs activate the IL-6/STAT3/miR-204-5p pathway by secreting IL-6, which supports cancer progression, increases the resistance of colorectal cancer to chemotherapeutic drugs and reduces drug-induced apoptosis." (PMID 33722297, 2021). "Previous studies have shown that Regorafenib inhibited TGF-β1-induced EMT in colorectal cancer by activating SHP-1-dependent P-STAT3 by directly dephosphorylating STAT3 on Tyr705 thus silencing the downstream pathway in in vivo and in vitro 2D models." (PMID 34638417, 2021). "For instance, TRIM14 accelerated the migration and invasion abilities of colorectal cancer cells through regulating SPHK1/STAT3 signaling." (PMID 33892646, 2021). "MiR-4449 promoted cell proliferation and JAK2/STAT3 signaling activity by inhibiting SOCS3 in colorectal cancer." (PMID 34691358, 2021). "To investigate the mechanism at the molecular level, we tested the STAT3 pathway in colorectal cancer cell-derived tumorspheres treated with 20 μM diHEP-DPA." (PMID 34573091, 2021). "Inhibition of the STAT3 pathway also reportedly induced cell-cycle arrest and apoptosis in colorectal cancer cells." (PMID 34769290, 2021). "The application of JAK/STAT3 inhibitors also greatly enhances the sensitivity of colorectal cancer cells to chemotherapy." (PMID 34895038, 2021).
colorectal cancer (continued). "Four ongoing clinical trials were found, involving tocilizumab, an anti-IL6Rα antibody with favorable results in preclinical studies, and napabucasin, a STAT3 inhibitor that is also under investigation in colorectal cancer." (PMID 34138876, 2021). "This study demonstrated that hypoxia augments activity and malignant behaviors of colorectal cancer cells through the STAT3/miR-19a/PTEN/PI3K/AKT axis." (PMID 34796092, 2021). "They showed PTPRT specifically dephosphorylated STAT3 at a tyrosine at amino acid Y705 and overexpression of normal PTPRT in colorectal cancer cells reduced the expression of STAT3 target genes." (PMID 34414233, 2021). "Recent studies have shown that LL1 suppresses the growth of colorectal cancer by block the activation of STAT3." (PMID 34059647, 2021). "In previous reports, inhibition of JAK1 and 2/STAT3 signaling was reported to induce apoptosis and cell cycle arrest in colorectal cancer cells." (PMID 34721022, 2021). "Our group previously demonstrated a potential role of Signal Transducer and Activator of Transcription 3 (STAT3) in mediating CRT resistance of colorectal cancer (CRC) cell lines." (PMID 33530306, 2021). "KIF20A maintains a set of malignant characteristics in colorectal cancer by activating the JAK/STAT3 pathway." (PMID 34595101, 2021). "The phosphorylation inhibition of STAT3 by CT treatment was reported in prostate, pancreatic, colorectal cancer, gastric, renal cell carcinoma, and malignant glioma." (PMID 33544704, 2021). "Similar to previous data in human and canine cancer cell lines, adding a selective STAT3 inhibitor reduced colorectal cancer cell’s death from 22 to 20 hours." (PMID 33544704, 2021). "Previous studies have indicated that hispidulin inhibits the Janus kinase 2 (JAK2)/STAT3 pathway by generating ROS in colorectal cancer cells, and downregulates the expression of the oncogene PIM1." (PMID 34356663, 2021). "Previous studies have mechanistically shown that flubendazole elicits antitumor effects by inhibiting STAT3 in triple-negative breast carcinoma and colorectal carcinoma." (PMID 34513827, 2021). "Small RNAseq was used to investigate differential microRNAs in colorectal cancer cell-derived tumorspheres and in a STAT3-knockdown strain." (PMID 33023006, 2020). "The SHP1 agonists SC-43 and SC-78 stimulate SHP1 to deactivate IL-6-induced STAT3 phosphorylation, thereby inhibiting colorectal cancer stem cells." (PMID 32792945, 2020). "For example, the tyrosine kinase inhibitor BCR-ABL can regulate LPS-induced NF-kB and STAT3 levels in human colorectal cancer cells." (PMID 32660121, 2020). "DUXAP8, upregulated by STAT3, also fueled migration and invasion of colorectal cancer by functioning as a ceRNA for miR-577 to regulate RAB14." (PMID 32185172, 2020). "We further demonstrate that IL-10 stimulates EMT in colorectal cancer cells by activation of the STAT3- and NF-κB pathways and by promoting cancer cell proliferation." (PMID 32222879, 2020). "The result is consistent with promotion of cell migration and invasion MMP-9 through the Jak2/Stat3/MMP9 signaling pathway in B7‐H3 stimulation in colorectal cancer." (PMID 33228717, 2020). "The immunohistochemistry images revealed that STAT3 showed low staining in colorectal cancer, but high staining in normal colon tissue." (PMID 32486001, 2020). "It is noteworthy that HIF-1α is previously reported to activate STAT3 by repressing miR-34a in colorectal cancer." (PMID 33681184, 2020).
colorectal cancer (continued). "In this current study, we also found betulinic acid responded to STAT3 expression in large intestine cancer." (PMID 32486001, 2020). "We illustrated the mechanism of WCAF and discovered that its anti-tumor activity in colorectal cancer is mediated by Leptin/STAT3/VEGF signaling and its interaction with the anti-angiogenic agent BEV." (PMID 33746736, 2020). "This study demonstrated that the downregulation of miR-30a-5p in colorectal cancer-derived tumorspheres is regulated by STAT3." (PMID 33023006, 2020). "It is revealed that STAT3 can regulate the expression of Cyclin D1 through directly targeting its promoter in colorectal cancer cells." (PMID 32194797, 2020). "Taken together, these results highlight that TCN inhibits various cancer-related features in colorectal cancer development in vitro by targeting STAT3, indicating that TCN is a promising STAT3 inhibitor that deserves further exploration in the future." (PMID 32422984, 2020). "Mcl-1 expression can be increased by STAT3 pathway in cholangiocarcinoma cells 20, colorectal cancer cells 22, melanoma cells 28 and gastric cancer cells." (PMID 31956373, 2020). "Gene expression of ALOX15 suppresses the TNF-α signaling pathway, IL-1β/NF-κB, and IL-6/STAT3, which play a major role in increasing colorectal cancer through chronic inflammation." (PMID 32986357, 2020). "In conclusion, a STAT3-miR-30a-5p-HSPA5 axis was observed against regorafenib-mediated apoptosis in colorectal cancer tumorspheres." (PMID 33023006, 2020). "It has been demonstrated that metformin inhibits angiogenesis by suppressing the JAK/STAT3 signaling pathway in esophageal squamous cell carcinoma, and aspirin exhibits anticancer effects by regulating STAT3 signaling in colorectal cancer." (PMID 32486001, 2020). "Phosphorylated molecules p-JAK2 and p-STAT3 are significantly increased in colorectal cancer cells overexpressing COX2 (cyclooxygenase-2)." (PMID 33198257, 2020). "In conclusion, our data indicate that STAT-3 and NF-κB are involved in the M2-TAM-promoted EMT process of colorectal cancer cells and that PA and Cer decrease the mRNA expression of STAT-3, NF-κB, and SNAI1." (PMID 32222879, 2020). "In colorectal cancer cells, IL-6 activated STAT3 to suppress the MIR34A gene via a conserved STAT3-binding site in the first intron and further promoted EMT and invasion." (PMID 33322216, 2020). "Another study demonstrated that FAM64A regulates STAT3 activation and is involved in Th17 differentiation, colitis and colorectal cancer development." (PMID 32932948, 2020). "PKM2 modulates the sensitivity of colorectal cancer cells to gefitinib through up-regulation of STAT3 activation." (PMID 33292198, 2020). "A previous study demonstrated that, in colorectal cancer, phosphorylation levels of STAT3 and JAK2 were inhibited by RPN2 siRNA 28, indicating that the JAK/STAT pathway was positively correlated with RPN2 expression." (PMID 31743606, 2020). "The activation of STAT3 by nuclear PKM2 reduces the sensitivity of colorectal cancer cells to tyrosine kinase inhibitor of the EGFR pathway." (PMID 33292198, 2020). "The fact that these actively proliferating tissues expressed high levels of Stat3 is in agreement with the well-known oncogenic activity of Stat3 in glioblastoma, colorectal cancer and leukemia." (PMID 32467235, 2020). "NFkB and STAT3 pathway play essential role in inflammatory response and link chronic inflammation to colorectal cancer." (PMID 32703189, 2020). "This study identified a STAT3-downstream micro RNA (miRNA) involved in drug resistance against regorafenib in colorectal cancer stem-like tumorspheres." (PMID 33023006, 2020). "In our previous study, ETV5 mediated-angiogenesis was demonstrated to be dependent upon the PDGF-BB/PDGFR-β/Src/STAT3/VEGFA pathway in colorectal cancer (CRC)." (PMID 33099574, 2020). "And the protein expression of STAT3 was significantly decreased in colorectal cancer and renal cancer compared with normal tissues." (PMID 32486001, 2020).
colorectal cancer (continued). "Berberine markedly decreased the levels of phosphorylated JAK2 and phosphorylated STAT3 in colorectal cancer cells and effectively interrupted the COX2/JAK/STAT signaling pathway, which was observed as a decrease in the level of metalloproteinases." (PMID 33198257, 2020). "Intriguingly, it has recently been shown that phosphorylated STAT3 is present in exosomes from 5-fluorouracil (5-FU) resistant colorectal cancer cells, which contributes to acquired 5-FU resistance." (PMID 32972405, 2020). "We have shown that TCN effectively inhibited STAT3 activation, suppressed its downstream target gene expression, and induced apoptosis in human colorectal cancer HCT 116 cells." (PMID 32422984, 2020). "FLCWK can inhibit the activation of STAT3 by reducing the production of IL-6, thereby increasing the occurrence of colitis-related colorectal cancer with 5-FU." (PMID 33082817, 2020). "Results generated from most STAT1 studies support the concept of STAT1 as a tumor suppressor in various cancers including colorectal cancer, which fulfills an opposite role to that of STAT3." (PMID 32422984, 2020). "Increased IL-6 expression has been related to advanced stages of disease and decreased survival in colorectal cancer patients, it activates JAKs with a subsequent activation of STAT3 through phosphorylation." (PMID 32422984, 2020). "The IL-6R/STAT3/miR-34a feedback loop was required for maintenance of the mesenchymal phenotype and promoted invasion and metastasis in colorectal cancer." (PMID 32872659, 2020). "STAT3 is oncogenic in colorectal cancer, as evidenced by the observation that mice with specific ablation of STAT3 in IECs develop fewer tumors in colorectal cancer." (PMID 32670290, 2020). "Our findings indicate that Jak/Stat3 signalling is needed for intestinal stem cell maintenance and possibly crucial in controlling Wnt/β-catenin-dependent colorectal cancer cell proliferation." (PMID 32467235, 2020). "The combination of curcumin and (-)-epigallocatechin-3-gallate (EGCG) has anti-angiogenic activities in colorectal carcinoma by blocking the Janus kinase/Signal transducer and activator of transcription 3/Interleukin-8 (JAK/STAT3/IL-8) pathway." (PMID 33173425, 2020). "In relation to colon cancer, it was shown that IL-6/STAT3-driven EMT in a colorectal cancer model requires miR-34a suppression." (PMID 31557902, 2019). "Nevertheless, few studies have focused on exosomal p-STAT3 in colorectal cancer and the selectivity of proteins transported by exosomes has not been fully understood." (PMID 31324203, 2019). "Although the authors excluded the contribution of VCP to the anti-inflammatory effects of azithromycin, it should be noted that VCP over-expression induces STAT3 phosphorylation in colorectal cancer cell lines." (PMID 31849581, 2019). "Recent studies revealed that the inhibition of STAT3 sensitized colorectal cancer cells to 5-FU treatment through down-regulating cyclinD1." (PMID 31324203, 2019). "An earlier finding showing that the IL-6R/STAT3/ miR-34a feedback loop promoted EMT in colorectal cancer prompted us to investigate the existence of the same feedback loop in HGSC." (PMID 31448054, 2019). "Here we show that STAT3 is activated in the HCT116 colorectal cancer cell line cultured as MCS, where cells grow at high density in 3D suspension structures." (PMID 30679726, 2019). "High levels of phosphorylated STAT3 are unfavourable for overall survival and can be correlated to lymph node metastasis in colorectal cancer patients." (PMID 30679726, 2019). "In the AOM and the Apc (Min/+) mouse models of colorectal cancer, the deletion of STAT3 in the intestinal epithelial cells reduced early adenoma formation (i.e., oncogenic role)." (PMID 31072360, 2019).
colorectal cancer (continued). "In line with our findings, Cheon and co-workers recently demonstrated for other KRAS mutant colorectal cancer cells a bypass mechanism of refametinib resistance to MEK inhibition involving the activation of STAT3 and MAPK triggered by MIF overexpression." (PMID 31557914, 2019). "Cancer stem cell populations were sorted out by CD51 (+) and CD133- (+) and we found that both NF-κB and STAT3 are phosphorylated in the colorectal cancer stem cell population." (PMID 31360301, 2019). "Dysregulation of the IL-6/STAT3 signaling pathway has an important role in the development of colorectal cancer." (PMID 30832202, 2019). "Altogether, these findings suggest that STAT3 is a direct transcriptional activator for HK2 in human colorectal cancer." (PMID 31655629, 2019). "We report a novel synthetic curcumin analog’s inhibition on cancer stem cell phenotype and telomerase activity by inactivation of STAT3 and NF-κB in colorectal cancer stem cells." (PMID 31360301, 2019). "For instance, the tyrosine kinase Bcr-Abl stimulates STAT3 (Ser727) phosphorylation via JAK/MEK signaling, whereas the Bcr-Abl kinase inhibitor ponatinib suppresses IL-6-stimulated STAT3 phosphorylation in human colorectal cancer (CRC) cells." (PMID 31655606, 2019). "JAK and STAT3 promote cell proliferation, invasion and migration in colorectal cancer through the regulation of cell adhesion molecules and growth factors." (PMID 31684858, 2019). "The anti-cancer effects of WFA on the proliferation and migration of colorectal cancer cell lines have been cited due to reduced transcriptional activity of STAT3 (signal transducer and activator of transcription 3)." (PMID 31731424, 2019). "Berberine significantly decreased the phosphorylated levels of JAK2 and STAT3 in colorectal cancer cells." (PMID 30987378, 2019). "In colorectal cancer, the activation of α7nAChR in tumor macrophages inhibits colorectal cancer metastasis through the JAK2/STAT3 signaling pathway." (PMID 31068932, 2019). "(2011) demonstrated that STAT3 was constitutively activated in colon cancer-initiating cells, and established the powerful rationale to develop STAT3 inhibitory strategies for treating advanced colorectal cancers." (PMID 30905249, 2019). "Taken together, these results indicated the function of p-STAT3 encapsulated by Exo/R in regulating 5-FU resistance in colorectal cancer cells in vivo." (PMID 31324203, 2019). "Studies have shown that p-STAT3, the activated form of STAT3, is elevated in various types of cancer, and it is a marker of poor prognosis for colorectal cancer patients." (PMID 31354479, 2019). "(2014) showed that STAT3-specific siRNA significantly sensitized colorectal cancer to chemoradiotherapy both in vitro and in vivo." (PMID 30905249, 2019). "Taken together, these data showed that the effect of the CC-MSCs on colorectal cancer progression was dependent on IL-6 and STAT3 activation." (PMID 29348540, 2018). "Recently, reports have found that inhibition of the JAK2/STAT3 pathway induces cell cycle arrest and apoptosis in colorectal cancer (CRC) cells." (PMID 30564118, 2018). "Signal transducer and activator of transcription 3 (STAT3) signaling is a major driver of colorectal cancer (CRC) growth, however therapeutics, which can effectively target this pathway, have so far remained elusive." (PMID 30572654, 2018). "Several oncogenic molecules are involved in the progression of colorectal cancers including signal transducer and activator of transcription 3 (STAT3)." (PMID 30597956, 2018). "In brief, our results indicate that CC-MSCs enhance colorectal cancer progression through the activation of IL-6/JAK2/STAT3 signaling." (PMID 29348540, 2018). "Our study showed that combination treatments of resveratrol and 5-FU inhibited STAT3 and Akt phosphorylation in human colorectal cancer cells." (PMID 30250641, 2018).